IL6 (interleukin 6)
Diseases named in the same sentence as IL6 in open-access papers (continued):
Sharing a sentence is not in itself a finding about the gene and the disease.
infection (continued). "Interestingly, this role of IL-6 appears to be primarily important early during a T-dependent immune response, as antibody levels in the absence of IL-6 are normal by day 15 post-infection." (PMID 21423809, 2011). "For IL-6 a significant reduction in the concentration was observed post H37Rv-infection only, whereas the observed reduction in IL-6 post Δ-mce1 H37Rv-infection, from 607 pg/ml to 271 pg/ml by 15 min post-infection and 258 pg/ml by 10 hrs, was not statistically significant." (PMID 22039457, 2011). "More recently, it was questioned whether lethality is only due to a cytokine storm because mice that lacked CCL2, IL-6 or TNF-α succumbed as often as wild-type mice to infection with a lethal H5N1 virus." (PMID 21314972, 2011). "Rather, IL-6-induced hepcidin expression occurred much earlier than that mediated by IFN-γ, suggesting that these two inflammatory cytokines may provide a concerted response to infection, and thus an additional means to fine tune the regulation of hepcidin." (PMID 21810240, 2011). "Furthermore, cytokine analysis showed that the IFN-γR−/− mice had significantly reduced levels of pro-inflammatory (IL-1α, IL-1β, and IL-6), IL-12p40, IL-17, and chemokine (G-CSF and CXCL1) production compared to WT mice during infection with C. neoformans strain H99γ." (PMID 21359196, 2011). "Interestingly, there was a trend towards increased concentrations of RANTES, IP-10, IL-6, and IL-8 over time post-infection, irrespective of the virus strain used, compared to mock-infected controls." (PMID 21272337, 2011). "Since IL-1β may induce IL-6 production by ECs, it is not clear whether IL-6 production by infected cells is a direct result of the infection or is induced by the IL-1β produced in response to infection." (PMID 20824217, 2010). "It was shown that HBV was recognized by KC, although the virus does not replicate in these cells, and that within hours post infection, this recognition leads to the activation of NFκB and subsequently to the release of IL-6 and other pro-inflammatory cytokines (i.e., IL-8, TNFα, IL-1ß)." (PMID 21994686, 2010). "As opposed to IFNγ and IL-6, the production of IL-17A could not be further induced by infection doses beyond 10×LD50." (PMID 20585449, 2010). "Law suggested that SARS-CoV, during infection of dendritic cells, evades the immune response by down-regulating expression of the anti-viral chemokines IFN-α, β and γ and IL-12p40, while simultaneously up-regulating that of others: for example, TNF-α, IL-6, MIP-1α, and IP-10." (PMID 20478047, 2010). "It was suggested that IL-6 could ensure an early control of virus replication, thereby limiting the activation of the adaptive immune response and preventing death of the HBV-infected hepatocytes in the early phase of infection." (PMID 21994686, 2010). "Taken together, these results suggest that in the absence of IL-6, there is an imbalance in the induction of early inflammatory modulators and that IL-6 likely functions as a regulator of the early immune response to infection." (PMID 19587788, 2009). "In the present study, we report that infection of human THP-1 monocytic cells with the vMyxM013-KO virus, unlike the parental MYXV, unexpectedly induced rapid and dramatic secretion of diverse pro-inflammatory cytokines such as TNF, IL-6 and MCP-1, all of which are regulated by NF-κB." (PMID 19851467, 2009). "Further, infection alters TLR responsiveness, as IL-12 production (as measured by ex vivo intracellular staining of CD11c+ DCs) in response to LPS stimulation is reduced, while IL-6, TNF-α and in particular, IL-10 all increase following infection with either nematode parasite." (PMID 19766674, 2009).
infection (continued). "Upregulation of inflammatory mediators, including cytokines and chemokines such as IL-1, IL-6, IL-8, IL-12, macrophage inhibitory protein-1/2, tumor necrosis factor-α (TNF) and recently also type I IFN has been observed in experimental and clinical infections with wt as well as with recombinant Ads." (PMID 19008951, 2008). "The data presented above revealed that in self-limiting infections (sublethal), the expression of both IFN-γ and IL-6 in CD11b+ cells increased significantly less in ΔyopH infection compared to pYV+ infection, suggesting that these cytokines might be necessary for control of pYV+ but not of ΔyopH." (PMID 18803824, 2008). "When placental histocultures were treated with BTSn, significant decreases only in IL-6 (p < 0.04), IL-8 (p < 0.05), MCP-1 (p < 0.01), GM-CSF (p < 0.05), MIP-1α (p < 0.05), and MIP-1β (p < 0.05) secretion were detected in histoculture supernatants collected at day 1 post-infection or coinfection." (PMID 18593480, 2008). "Although NNIS scores, in association with other acute-phase proteins such as CRP, albumin and prealbumin, and with IL-6, were not the most effective tool, they may enable more accurate prognoses for postoperative infection." (PMID 17505683, 2007). "Even in the absence of overt infection or inflammation, many ESRD patients show increased levels of acute-phase proteins, such as C-reactive protein (CRP), ferritin, fibrinogen, and/or interleukin-6 (IL-6), associated with low serum albumin levels." (PMID 17206511, 2007). "Furthermore, in comparison with CRP or IL-6, presepsin exhibits a faster kinetic response, being detectable within the early hours of infection onset, whereas CRP may remain non-specifically elevated." (PMID 40804836, 2025). "Research has shown that inflammatory factors such as IL-1β, IL-6, IL-8, and TNF-α can induce and recruit various types of white blood cells to participate in immune responses, which may lead to tissue damage and affect the healing of infections if present long-term." (PMID 40529353, 2025). "Additionally, PGD2 upregulated both IL-6 and IL-10, regardless of the infection stage." (PMID 40874199, 2025). "The differential expression of SAA, IL-1β, and IL-6 was statistically nonsignificant at most time points following Ich infection, suggesting that these molecules may primarily be activated during the acute phase of infection." (PMID 40509043, 2025). "Indeed, the evolutionarily conserved pyrogenic response to infection is known to stimulate the immune response partly by promoting lymphocyte transendothelial migration across HEVs via increased luminal display of CCL21 (and ICAM1) under the influence of IL6 trans-signaling." (PMID 41216593, 2025). "Additionally, the levels of CRP and IL-6, which are more responsive to systemic inflammation and immune activation, were significantly elevated, further supporting the likelihood of an inflammatory response related to RP rather than infection." (PMID 40895557, 2025). "Furthermore, Simmental cows showed higher levels of IL-6 with infection than without infection." (PMID 40302747, 2025). "Despite these results, the 20% concentration was maintained for both the viability assay on infected cells and the IL-6 ELISA experiments, as the presence of bacterial pathogens capable of metabolizing certain CFS components could still yield beneficial effects in preventing infection outcomes." (PMID 40351306, 2025). "In addition, Trem2-/-, but not wildtype mice exhibited higher IL-6 following infection." (PMID 39250507, 2024). "As infection is difficult to rule out at the time of admission, we recommend that these patients are treated with both broad-spectrum antibiotics and anti-inflammatory agents upon admission, and if not responsive to corticosteroids, potential treatment with IL-6 inhibitors should be considered." (PMID 38974986, 2024). "Therefore, the overexpression of IL-6 prior to infection may induce this negative loop before it leads to a cytokine storm." (PMID 39062668, 2024).
infection (continued). "Further analysis using the ROC curve found that the AUC of IL‐6 to distinguish the effectiveness of anti‐infection at 12 h was 0.895, whereas PCT and CRP were failed to predict the antimicrobial efficacy, which may be associated with the unique characteristics of these three biomarkers." (PMID 38967137, 2024). "The PBS group showed high levels of inflammatory cytokines including IL-6, IL-18, IL-12 p70, IFN-γ, and TNF-α as well as chemokine GMCSF, which may suggest enhanced vascular permeability and increased infiltration of innate immune cells in response to infection in unvaccinated animals." (PMID 38711520, 2024). "Although we did not observe significant differences in IFN-α, IL-6, or other cytokine levels between patients with and without naAbs, this may be related to the fact that we did not detect a peak in cytokine elevation during the early stages of infection." (PMID 38462559, 2024). "Indeed, we observed that the most considerable augmentation of pro-inflammatory IL-1β, IL-6, IL-15, IL-18, IFN-γ, eotaxin, GRO-α, IP-10, MCP-1, MIP-1α, MIP-1β, and regulatory IL-1RA, occurred at the terminal stage of the disease (7 days post-infection) in our rhesus macaques." (PMID 38035334, 2023). "However, no increase in IL-6 levels was observed for infection of the TLR2−/− BMMs." (PMID 37404047, 2023). "Therefore, the diagnostic value of inflammatory indicators for infection in SLE patients needs to be confirmed by more studies, but in our study, inflammatory indicators such as CRP, PCT, and IL-6 were significantly elevated in the non-surviving group of patients." (PMID 37051301, 2023). "Thus, we hypothesized that the differential expression of Il6 and Tnf during the late stage of infection was not induced directly by NSP9 but rather by other antiviral genes (such as Ifnb, Isg15, and Ccl5) produced via the activated type I IFN pathway." (PMID 37854611, 2023). "In addition, the same was held with SVCV infection, we found that bazedoxifene/Stattic/17-AAG/AUY922/PGE2/VPA treatment inhibits or increases the SVCV genome entry, and the transcription of pro-inflammatory cytokines (IL6, TNF-α, IL1β) accordingly in a dose-dependent manner." (PMID 37099596, 2023). "RT-PCR analysis showed that lytic infection of KHV in common carp brain (CCB) cells or temperature-switch treatment of koi (10°C to 20°C) significantly induced the expression of IL6, suggesting that temperature-dependent IL6 expression may participate in the lytic infection of KHV." (PMID 37099596, 2023). "Overall, the ability of pantethine to reduce the infection-induced increases in MAVS, IRF3 and STING expression could explain the antiviral and anti-inflammatory effects of pantethine, which significantly inhibited IFNβ, TNFα and IL6 expression in infected Calu-3a cells." (PMID 36754974, 2023). "In addition, some studies did not report infection status, i.e., if ‘acute infection’ was present, in their exclusion criteria which might affect the prognostic value for IL-6." (PMID 37884903, 2023). "However, neither gonadectomy nor infection changed the IL-6 concentration." (PMID 37628731, 2023). "Interestingly, only IL-6 did not return to baseline at the end of the infection period." (PMID 36893126, 2023). "However, overexpressing IL-6 and trappin-2 in vivo could prevent death from PAO1 infection." (PMID 36312971, 2022). "Similarly, we investigated the changes in the levels of ileal interleukin-6 (IL-6), which displayed a significant rise in the ileum of PA14-infected mice (P < 0.001) and a marked decrease in the D88 administration group and the mvfR mutant infection groups (P < 0.05 and P < 0.001, respectively)." (PMID 36042245, 2022). "However, despite IL-6 acting as a potent pro-inflammatory cytokine on T cells by promoting Th17 differentiation, these subpopulations of T cells do not represent the most effective type of response in combating HCV and may favor the persistence of infection." (PMID 35336914, 2022).
infection (continued). "With this notion, IL-6 blockade may not be a successful strategy to cure the infection." (PMID 35619180, 2022). "However, no increase in IL-6 RNA expression was observed at 48 h post-infection (data not shown)." (PMID 36128218, 2022). "However, infection or inflammation may amplify the action of LMW-HAs via interactions with hyaladherins, leading to an increase in the secretion of cytokines (TNF-α, IFN-β, IL-6), chemokines (IL-8), ROS, or enzymes (NE, MMP-9, MMP-10, MMP-12)." (PMID 35625586, 2022). "Additionally, it is known that IL-6, CCL2 and IL-10 could be recognized as biomarkers for P. vivax acute infection phase, however, our study is unique in proposing a coefficient combining levels of four cytokines and chemokines as biomarkers for P. vivax severity." (PMID 36178979, 2022). "In addition, we also found that the mRNA transcript levels of pro-inflammatory cytokines IL-1β, TNF-α, IL-6, and IL-12, and anti-inflammatory cytokines IL-4, and IL-10 tended to decrease (p < 0.05 or p < 0.01) in the cats from the feIFN-ω’ treatment group, compared with the FPV infection group." (PMID 35068319, 2022). "The top three primary infection sites of inflammatory indicators (PCT and IL-6 decline) in this study were urinary tract, abdominal cavity, and skin and soft tissue, indicating that oXiris-CHFA treatment may be more clinically effective for infections originating from these regions." (PMID 36249210, 2022). "In addition, the infection of healthy peripheral blood mononuclear cells with ZIKV induces the production of soluble IL-6, IL-8 and the IL-9 cytokines, accompanied by a partial or complete lack of type I, II, and III interferons, essential for viral clearance and effective immune response." (PMID 33776990, 2021). "However, in our work, we could not find that MR-proADM provided more data than PCT and IL-6, probably because we did not include any patients with organ failures or very severe infection." (PMID 34828740, 2021). "Remarkably, we found higher TNF, IL-1β, IL-6, and IL-10 in lung homogenates of LysM-cre × Hif1αfl/fl mice when compared with Hif1αfl/fl control mice at 12 hours after inoculation, but these differences in pulmonary cytokine levels were not present after 40 hours of infection." (PMID 34393650, 2021). "In addition, systemically reconstituted animals with IL-6(-/-) BMMCs improved survival compared to those reconstituted with IL-6(+/+) BMMCs, suggesting that degranulation and IL-6 release from MCs located distant to the site of infection play a detrimental role during CLP-induced infection." (PMID 34211473, 2021). "In addition, IL6 is often found in the CSF after infections with Gram-negative bacteria." (PMID 34863201, 2021). "While elevation of IL-6 and other inflammatory biomarkers may operate through CB1-independent pathways, these results suggest a role both for alcohol alone and the combination of alcohol and cannabis in increased morbidity and mortality in the setting of infection by a pulmonary pathogen." (PMID 34440011, 2021). "Regardless of whether intrapartum fever occurs or not, if the parturient receives epidural analgesia during delivery, the levels of IL-6 and IL-8 are significantly higher than levels of these factors at admission, and this phenomenon is not related to infection." (PMID 34172031, 2021). "Yet, most studies quantify IL-6 only at patient admission, a strategy that may not be appropriate to accurately predict the outcome or to guide treatment due to the dynamic inflammatory process occurring during infection with SARS-CoV-2." (PMID 33679753, 2021). "To examine whether the moderate modulation of TH17 cells in the absence of IL-6 is associated with an impaired protective immune response against Mtb, we further analyzed the integrity of TH1 immunity and the bacterial loads during the course of infection." (PMID 33375150, 2020).
infection (continued). "Therefore, in order to evaluate the role of IL-6 in host resistance against Brucella infection in vivo, we infected wild-type and IL-6 KO mice with B. abortus, and CFU counts were analyzed at 1 and 6 weeks post-infection in spleens, an organ that serves as a niche for this bacterium." (PMID 33322581, 2020). "Because HTLV-1 promotes the production of cytokines such as interferon-gamma, tumour necrosis factor-alpha, and interleukin-6, through the activation of nuclear factor-κB and cyclic AMP response element-binding protein, inflammatory factors might be induced even during asymptomatic infection." (PMID 32706758, 2020). "In addition to reducing the bioburden in wound tissue, AMPs can modulate the immune response by stimulating leukocyte recruitment to the site of infection and the production of immune mediators GM-CSF, and inhibit S. aureus-evoked expression of the pro-inflammatory cytokines of TNF-α and IL-6." (PMID 33042031, 2020). "Additionally, plasma IL-6 levels were not significantly related to the frequency of Tfh cells, ICOShigh Tfh cells, or PD-1high Tfh cells or to the OD values of plasma MeV-specific IgM antibodies in the patients with acute-phase MeV infection (data not shown)." (PMID 32873255, 2020). "Hence, the deletion of IL-6 had no influence on the outcome of an aerosol infection with Mtb." (PMID 33375150, 2020). "Thus, lower eye disease in IL17RC−/− mice could be associated with the absence of neutrophils, leading to reduced IL-6 expression at the site of infection." (PMID 32516406, 2020). "However, there is no consensus on reported cytokine levels, particularly IL-6 (approximate range = 10pg/mL to >20 ng/mL), which could be attributed to analytical method or infection time-point." (PMID 34192268, 2020). "However, there was no change of TNF-α and IL-6 production in LL37 treated-macrophages in the absence of infection vs. in untreated group, neither in macrophages infected by Aspergillus pre-treated with LL37 or sL37 for an hour vs. by untreated A. fumigatus (data not shown)." (PMID 30842778, 2019). "Additionally, the same authors also found viral RNA in the CSF of a different cohort of hRSV-infected patients, with increased levels of IL-6, IL-8, CCL2, and CCL4, suggesting that these inflammatory mediators may play a critical role during the hRSV-infection in the CNS pathogenesis." (PMID 30936869, 2019). "As EHDV-TAU kills LNCaP-based cells with high efficiencies (i.e., upon productive infection of untreated cells or upon non-productive infection in IL-6-treated LNCaP-JAK1 cells), we could not address the question if IL-6 sensitizes cells to virally induced cell death." (PMID 29441069, 2018). "Contrary to hypothesis one (that calves which died perinatally without diagnosed infection in utero would exhibit a similar acute phase response to calves which survived), IL-6 concentrations (plasma and abomasal fluid) were higher in live compared to dead calves." (PMID 30382887, 2018). "While infection did not cause a cytopathic effect, a significant reduction of key osteogenic markers such as ALP, RUNX2, calcium contents and increased expression of IL6 in ZIKV-infected MSCs implicated a delay in osteoblast development and maturation, as compared to uninfected controls." (PMID 30451958, 2018). "In addition to lipocalin-2, equine MSCs from all sources examined expressed the immunomodulatory genes, MCP-1, IL-6, IL-8, and CCL5, suggesting that these cytokines may contribute to the reported ability of equine MSCs to limit infection indirectly by recruiting and activating immune cells." (PMID 30044182, 2018). "Similarly, neither infection nor treatment altered the levels of serum TNF or plasma IL-6." (PMID 30072754, 2018).